MMP9 (matrix metallopeptidase 9)
Diseases named in the same sentence as MMP9 in open-access papers (continued):
Sharing a sentence is not in itself a finding about the gene and the disease.
glioma (continued). "To determine whether the high MMP9/oxidative phosphorylation population (cluster 6) is relevant in human glioma, we obtained bulk RNA-Seq data sets from TCGA with combined low-grade glioma (LGG) and high-grade GBM." (PMID 36757811, 2023). "Moreover, mangiferin promoted the expression of miR-15b, as well as reduced the level of glioma cell MMP-9 expression." (PMID 38137424, 2023). "MMP-9 expression correlates directly with tumor grade and indirectly with survival in glioma." (PMID 37370851, 2023). "Furthermore, the migration of glioma cells was attenuated by adding KPF-BBR or KPF-ABR by the MMP-9 expression level evaluated by qPCR, especially KPF-ABR." (PMID 37445894, 2023). "In a similar way, it has been suggested that even IL-17A might control glioma cell invasiveness by inducing the overexpression of MMP-9/-2 via PI3K/AKT." (PMID 36980765, 2023). "Additionally, the expression of MMP-2 and MMP-9 was observed to be significantly higher in recurrent gliomas than in primary gliomas, and correlated with increased resistance to radiotherapy." (PMID 36675073, 2023). "By transplanting CD133-positive and CD133-negative U87 glioma cells in zebrafish, our previous study indicated that glioma stem cells have higher invasion ability than differentiated glioma cells through regulating MMP9 expression." (PMID 36483593, 2022). "Moreover, Bmi-1 increases luciferase activity of the MMP9 promoter-driven reporter gene containing an NF-κB binding site, which promotes MMP9 transcription levels in glioma cells." (PMID 35897796, 2022). "Finally, MMP9 mean protein level was significantly higher in the serum of glioblastoma compared with grade III glioma patients, whereas MUC4 mean protein level was minimally elevated in higher glioma grades (III and IV) compared with control." (PMID 36400876, 2022). "The findings showed that a reduction in Pgp efflux in glioma cells could be achieved by suppressing the expression of miR-211 and/or MMP-9." (PMID 35586209, 2022). "Western blot analysis demonstrated that the protein levels of LASS2 and TIMP2 were apparently elevated, accompanied by reductions in SPHK1, MMP2, and MMP9 protein levels, in glioma xenografts derived from U-87 MG-pLV-LASS2 cells compared with those derived from U-87 MG-pLV cells." (PMID 35517425, 2022). "Moreover, through performing ROC analysis, we found that HOXC6, MMP9, SHOX2 and MYOD1 had a high diagnostic value (AUC>0.7) to distinguish primary and recurrent glioma tissues." (PMID 36118887, 2022). "One such research involves miRNA miR-211 and MMP-9 in glioma." (PMID 35586209, 2022). "In general, EGFR interacts with members of the mucin family in cancer, and as such, MUC4 may physically interact with EGFR in a ligand-dependent manner, leading to downstream signalling and MMP9-mediated glioma initiation and progression." (PMID 36400876, 2022). "We demonstrated that MUC4 and MMP9 are both significantly upregulated during glioma progression." (PMID 36400876, 2022). "A recent study demonstrated that EGF-mediated activation of MMP-9 occurred through increased PI3K/Akt, ERK1/2, and STAT3/STAT5 signalling in glioma cells, leading to NF-κB localisation to the promoter of the MMP-9 gene and promoting GBM migration and invasion in vitro." (PMID 36497413, 2022). "Moreover, MMP-2 and MMP-9 have a synergistic impact on the breakdown of endothelial basement membrane in gliomas and facilitate the release of ECM-bound VEGF." (PMID 35884733, 2022). "Our study also found that curzerene downregulated the expression of MMP9 in glioma." (PMID 35048517, 2022). "It is therefore worth exploring whether there is a similar relationship between GSTA4 and MMP9 in glioma." (PMID 35048517, 2022). "Further finding also revealed that MMP-2 and MMP-9 may be responsible for glioma recurrence and malignancy." (PMID 35586209, 2022).
glioma (continued). "The MUC4/MMP9/EGFR combined low expression significantly predicted better survival in glioma patients in comparison with the ‘double high’ group and the difference was again more significant than the previous analysis that combined MMP9 and MUC4 only (without EGFR) (p = 0.004, Log-rank)." (PMID 36400876, 2022). "In gliomas, previous studies suggested that MMP9 could be released by microglial cells, macrophages, or neutrophils." (PMID 34980260, 2022). "Curzerene can induce apoptosis by inhibiting the expression of GSTA4 in gliomas, and it can downregulate the proliferation, invasion, and migration of gliomas by inhibiting the phosphorylation and activation of mTOR and the expression of MMP9." (PMID 35048517, 2022). "In addition, blocking MMP-9 expression by anti-mRNA led to the inhibition of cancer cell invasion and angiogenesis in human glioma cells." (PMID 36142326, 2022). "One could also imagine, that MMP9 released by other cell types in the tumor bulk like endothelial cells, neutrophils and glioma cells compensates, at least in part for its reduction in GAMs." (PMID 35992852, 2022). "Additionally, the extracellular matrix remodeling molecule matrix metallopeptidase 9 (MMP9) was significantly upregulated in the LPPR5OE glioma." (PMID 35328529, 2022). "Finally, we explored the potential of MUC4 and MMP9 as serum biomarkers by measuring protein levels in serum samples of high-grade glioma patients and non-glioma (control) individuals." (PMID 36400876, 2022). "Similarly, Bmi-1 promotes glioma invasion by activating NF-κB/MMP3 or NF-κB/MMP9 signaling pathways." (PMID 35897796, 2022). "Our results indicate that MMP9-expressing cells could increase in number during glioma progression, as observed in other types of cancer." (PMID 36400876, 2022). "The expression of HOXC6, MMP9, SHOX2 and MYOD1 was associated with hypoxia degree in glioma tissues and in recurrent cases, had a remarkable diagnostic value and a significant relationship with disease free survival in glioma patients." (PMID 36118887, 2022). "The downregulation of MMP9 in cell lines and tumor tissues may explain the mechanism by which curzerene inhibits glioma invasion and migration." (PMID 35048517, 2022). "Luo and coworkers have recently shown that STC1 levels directly correlate with those of matrix metalloproteinases (MMP)-2, MMP9, and vimentin in gliomas, and these authors hypothesized that STC1 augments the invasive capacities of glioma cells." (PMID 34394104, 2021). "We further found the MMP-9 mRNA was partially reduced by MTCH2 knockdown, indicating that the reduced MMP-9 expression may contribute to the decreased invasion activity of glioma cells." (PMID 33509092, 2021). "Moreover, the activation of TLR2 expressed on microglia, has triggered the release of matrix metalloproteinases (MMP2 and MMP9), degrading the extracellular matrix and facilitating the invasion of glioma cells." (PMID 33802571, 2021). "Further, western blot was used to detect the changes of the expression of VM formation-related proteins MMP2, MMP9, and VE-cadherin in glioma cells after HNRNPD knockdown, we found that compared with HNRNPD(−)-NC group, the expression of the proteins decreased significantly in HNRNPD(−) group." (PMID 33542193, 2021). "Another lncRNA metastasis-associated lung adenocarcinoma transcript 1 (MALAT1) inhibits cell proliferation and invasion through the downregulation of extracellular signal-regulated kinase (ERK), matrix metalloproteinase 2 (MMP2) and MMP9 in U87 and U251 glioma cells and glioma nude mice models." (PMID 34202078, 2021). "Here, we report that the peptide UII and its receptor UT, expressed in malignant high-grade gliomas, promote angiogenesis and tumor vascular abnormal phenotype via up-regulation of mesenchymal factors including αvβ integrins and MMP-9, accompanying tumor growth, proliferation, and hypoxia/necrosis." (PMID 33937253, 2021).
glioma (continued). "In addition, inhibition of NF-kB in glioma cells decreases MMP-9 and VEGF expression, leading to invasion and angiogenesis blockade." (PMID 34685761, 2021). "The positive action of Api was also evaluated in U87 glioma cells, where it was found to reduce tumor cell metastasis and invasion, inhibit MMP-9 mRNA levels, and downregulate nuclear factor-KB (NF-KB), a known regulator of MMP-9 expression under inflammatory conditions." (PMID 33498927, 2021). "Among MMPs, MMP‐2 and MMP‐9 have been indicated as having an upregulated expression in glioma." (PMID 33300633, 2021). "Furthermore, the results obtained from the Western blotting assay showed that the protein expressions of N-cadherin, Vimentin, and MMP9 were upregulated, whereas E-cadherin expression was downregulated in glioma cells treated with exosomes." (PMID 33982667, 2021). "miR-138 and -210 regulate HIF genes, while miR-335 was reported to control MMP9 in glioma." (PMID 33919449, 2021). "Thus, it has been gradually accepted that MMP2 and MMP9 are candidate biomarkers for monitoring chemotherapy in high-grade glioma as well as indicating poor prognosis in glioma recurrence." (PMID 33889541, 2021). "We hypothesized that inhalational anesthetics might modulate the HIF-1α and MMP9 cell signaling/pathway in glioma cells via miRNA expression changes." (PMID 33919449, 2021). "Western blot was used to detect the changes of the expressions of VM-associated proteins in glioma cells, we found that the expression of MMP2, MMP9, and VE-cadherin were significantly reduced after overexpression of miR-651-3p and the anti-miR-651-3p group showed an oppisite effect." (PMID 33542193, 2021). "Furthermore, MMP9 expression in tumor tissue was correlated with the clinical tumor stages/grades and clinical outcome in glioma." (PMID 33919449, 2021). "The researchers concluded that MMP-2 and MT-MMPs might regulate glioma invasiveness, while MMP-9 plays a crucial role in angiogenesis within the tumor." (PMID 34638718, 2021). "Importantly, interference with CD147 expression significantly reduced the secretion and expression of MMP-2 and MMP-9, which reduced the proliferation of glioma cells induced by psychological stress." (PMID 33178600, 2020). "Increased expression of MMP-9 has been found in glioma tissues." (PMID 32158355, 2020). "Interestingly, pharmacological inhibition of MMP-9 and uPAR has resulted in the suspension of cell migration of glioma cells in preclinical studies." (PMID 33022958, 2020). "Thus, MMP9 is considered as an important regulatory factor for the migration and invasion of gliomas." (PMID 32158355, 2020). "IKKε knockdown is involved in the decreased MMP2 and MMP9 production in glioma cells." (PMID 32064021, 2020). "Kaji T showed that MMP-2 and MMP-9 were highly expressed in glioma cells." (PMID 33178600, 2020). "Some scholars speculate that it is regulated by the MAPK/ERK pathway because EGFRvIII is known to activate the extracellular signal-regulated kinase ERK 1/2 in glioma cells, which is a direct regulator of MMP-9 secreted by glioma cells." (PMID 33511267, 2020). "Co-transfection of ZRANB2(−) cells with SNHG20(−) could strongly decrease the expression of MMP1, MMP9, VE-Cadherin and strongly inhibit the abilities of proliferation, migration, invasion and VM of glioma cells." (PMID 30744670, 2019). "Moreover, an in vivo study using human glioma U-87 cells xenografted into athymic mice showed that curcumin is able to suppress glioma angiogenesis through inhibiting MMP-9 and downregulating endothelial cell markers (CD31 and CD105 mRNA)." (PMID 30818786, 2019). "The MMP-2 and MMP-9 received particular attention given that their increased expression appeared related to the malignant potential of several types of cancer, including human gliomas." (PMID 31130597, 2019). "Our results show that an Akt/MMP2/MMP9 axis potentially regulates VM formation in glioma." (PMID 31754182, 2019).
glioma (continued). "Down-regulation of PEBP1, also known as the Raf-1 kinase inhibitor protein (RKIP), is associated with glioma progression, and it has been demonstrated that RKIP, by inhibiting MMP-2 and MMP-9 expression, markedly reduces the ability of glioma cells to migrate and invade." (PMID 30845786, 2019). "The potential underlying mechanism may involve upregulation of miR-16 and downregulation of matrix metalloproteinase-9 (MMP-9), which are differentially expressed in glioma tissues and cells compared with healthy controls." (PMID 31178721, 2019). "In addition, CBX7 was found to regulate negatively migration and invasion via upregulation of E-cadherin and downregulation of matrix metalloproteinase (MMP)-2, MMP-9, and vimentin in glioma." (PMID 31709304, 2019). "The activated complement system signaling may provide an alternative mechanism for the NF-κB mediated overexpression of MMP-2 and MMP-9 in glioma cells by means of C5a-C5aR." (PMID 30208949, 2018). "In accordance with this effect, we also found that CXCL16 stimulation increased the expression level of the matrix metalloproteinases mmp9 and mmp2 (n = 6, p < 0.05; Student's t-test), whose activity is reported to be involved with the invasion ability of glioma cells." (PMID 30542347, 2018). "C1q may activate the canonical Wnt/β-catenin signaling pathway, which increases MMP-2 and MMP-9 expression by glioma cells." (PMID 30208949, 2018). "Our PLA study revealed close localization of NHE1 and MMP-9 in glioma tumors, which could promote invasion/proliferation of glioma cells via activating MMPs." (PMID 30262908, 2018). "In addition, myeloid-derived granulocytes and monocytes are also the major source of MMP9 expression in gliomas tissues." (PMID 30262908, 2018). "In addition, miR-146a which was predicted to target SMAD4, was downregulated in microglia exposed to glioma conditioned medium treatment and regulated the expression levels of tumor supportive gene MMP9 in microglia." (PMID 29861845, 2018). "Moreover, it has been reported that PF inhibited proliferation and induced apoptosis of human glioma cells via upregulating microRNA-16 and downregulating matrix metalloproteinase-9 (MMP9)." (PMID 29423667, 2018). "In humans, MMP-9 is upregulated in GBM, and MMP-9 is a candidate biomarker for high-grade glioma." (PMID 29029486, 2017). "The molecular docking and in vitro studies suggest that the MMP-9 inhibitory effects of compounds 8 and 9 may play an important role in lung adenocarcinoma and glioma treatment." (PMID 28677624, 2017). "Knocked down Collagen XVII expression in glioma cell lines resulted in decreased tumor invasiveness, along with significant reduction of MMP9 expression, while increased Collagen XVII expression promotes invasive activities of glioma cells and associated with GBM recurrences." (PMID 29156757, 2017). "MMP-2 and MMP-9 are negatively correlated with the prognosis of glioma patients." (PMID 28701209, 2017). "Thus, we investigated the protein profiles of PD-L1, VEGF, MMP-9 and KI-67 in glioma patients according to the patients' clinical characteristics, and explored the correlations in the expression of these proteins." (PMID 28591697, 2017). "Addition of an MMP-9 agonist antibody in U87 glioma cells reduces the efficacy of mangiferin." (PMID 28464819, 2017). "Meanwhile, since MMP9 faciliates migration of various cancers, we then examined whether it also implicated in PLD1-resultant migration of glioma cells." (PMID 28915652, 2017). "As regulators of cell adhesion and invasion, MMP2 and MMP9 are closely involved in augmentation of the invasive capability of glioma cells and correlate with the degree of histologic malignancy and clinical outcome, whereas Ki67 indicates the proliferative ability of the tumor." (PMID 28287612, 2017).
glioma (continued). "Another member, MT1E, could modulate the motility and invasion of a human glioma cell line by upregulating MMP9 as well, and this interaction was also related to an association between MT1E and NF-κB." (PMID 28109307, 2017). "Glioma-derived versican converts microglia into a pro-tumorigenic phenotype characterized by the upregulation of MMP9 and MMP14 (as observed here in response to LPA); in particular, MMP14 promotes activation of GBM-derived MMP2 that favors the invasive potential of malign glioblastoma cells." (PMID 29258556, 2017). "In U87 glioma cells, miR-15b regulates the expression of matrix metalloproteinase (MMP)-9." (PMID 28464819, 2017). "Moreover, HOXA7-siRNA inhibited migration and invasion in vitro, and downregulated MMP9 at the protein level in U251 glioma cells." (PMID 27677590, 2016). "Additionally, that report showed that glioma stem cells treated with miR-211- and shRNA-specific for MMP9 (pM) had increased drug retention capacity." (PMID 27022952, 2016). "In addition, hyaluronic acid, which is a glycosaminoglycan that binds to cell surface CD44, also induces MMP-9 expression in glioma cells via activation of the FAK signaling pathway." (PMID 27602495, 2016). "These experiments demonstrated that MMP9 directly impacts the survival of glioma patients." (PMID 27022952, 2016). "Our results indicated that MMP9 expression is correlated with glioma grade (p<0.0001)." (PMID 27022952, 2016). "We thus hypothesized that IL-6 was also involved in regulating MMP14 expression through the activation of MMP2 or MMP9 in glioma." (PMID 27613828, 2016). "We also examined PCNA and MMP9 expression in glioma tissues by using Western blot and RT-PCR." (PMID 26378521, 2015). "MMP-9, an important member of the matrix metalloproteinase family, plays a critical role in extracellular matrix degradation, invasion and metastasis in basal-like triple negative breast cancer, gastric cancer and glioma." (PMID 25797250, 2015). "Moreover, MMP-9, MMP-9/NGAL, and MMP-9 Dimer activity were weak or undetectable in most Postop-1w urine samples, suggesting that removal of the glioma tumor eliminates MMP-9 activity in patient urine samples." (PMID 26663949, 2015). "We also reported that GCN5 expression was correlated with PCNA and MMP9 in glioma tissues." (PMID 26378521, 2015). "In addition, GCN5 knockdown reduced expression of p-STAT3, p-AKT, PCNA and MMP9 and increased the expression of p21 in glioma cells." (PMID 26378521, 2015). "Thus, the elevation of urinary MMP-9/NGAL activity after surgery was indicative of tumor relapse in our cohort of glioma patients." (PMID 26663949, 2015). "Therefore, we have measured MMP-9/NGAL activity in glioma tissue and urine samples collected before and after surgery of glioma patient to assess the relationship of MMP-9/NGAL activity levels and disease progression and therapeutic response." (PMID 26663949, 2015). "In addition, previous studies have shown that MMP-9 plays an important role in the invasion process of glioma cells." (PMID 25163530, 2014). "The malignant transformation of glioma cells is accompanied by increased expression of MMP-9." (PMID 25163530, 2014). "Nuclear gelatinase B/MMP-9 has been reported in human gliomas, astrocytomas and neuroblastomas." (PMID 24473089, 2014). "Similarly, blocking MMP-9 function sensitized colon adenocarcinoma cells to phorbol-esters and glioma cells to Fas-induced apoptosis." (PMID 24956101, 2014). "Moreover, recent studies demonstrated that a number of cell cycle-related and invasion-associated genes are regulated by IGF-1R, including CCND1 and MMP-2/MMP-9 in human glioma and head and neck cancer, which function through MAPK and PI3K/AKT pathways." (PMID 24378652, 2014). "Because α9β1 integrin plays a crucial role in MMP-9 and uPAR-mediated cell migration in glioma, we hypothesized that MMP-9 and uPAR utilize iNOS via α9β1 integrin to arbitrate cell migration." (PMID 24325546, 2013).